IGF1R (insulin like growth factor 1 receptor)
Diseases named in the same sentence as IGF1R in open-access papers (continued):
Sharing a sentence is not in itself a finding about the gene and the disease.
breast cancer (continued). "These investigators demonstrated that the growth inhibition mediated by trastuzumab was lost in breast cancer cells having high HER2 and IGF1R levels." (PMID 35800378, 2022). "Accumulating γH2AX foci were also induced by IGF-1R depletion in MCF7 cells, and by xentuzumab treatment in a second ER+ breast cancer cell line, ZR-75-1, consistent with our previous findings in prostate and breast cancer cells." (PMID 34773074, 2022). "In breast cancer, then a downstream molecule of the AKT/mTOR pathway phosphorylates ERα which binds to promoter of target genes, and upregulates IGF-1, IGF-1R." (PMID 35784325, 2022). "NR2F1-AS1 was shown to act as a ceRNA by sponging miR-338-3p, preventing it from downregulating IGF-1; the resulting increase in IGF-1 activated IGF1R in endothelial cells, increasing ERK signaling and breast cancer angiogenesis." (PMID 35597813, 2022). "For example, one that is important in resistance is the insulin-like growth factor I receptor (IGF-1R), which is overexpressed in several solid tumors including in about 43–50% of primary breast cancers." (PMID 36291900, 2022). "However, IRS-2 is recruited to and activated by additional surface receptors, including integrins, growth hormone receptor and cytokine receptors, suggesting that membrane IRS-2 staining in breast cancer could represent activity of IGF-1R-dependent and -independent pathways." (PMID 36556357, 2022). "Since breast cancer progression is closely linked to EGFR tyrosine kinase signal; it can be speculated that diosgenin-mediated Rap1 signal could attenuate tumor invasion and metastasis; was observed to be modulated via the modulation of three genes i.e., PDGFRB, IGF1R, and FGFR2." (PMID 36686654, 2022). "To confirm this effect, we first tested IGF ligand antibody xentuzumab (BI-836845), and IGF-1R tyrosine kinase inhibitor BI-885578 in MCF7 breast cancer cells." (PMID 34773074, 2022). "In breast cancer cells, t-DARPP activates insulin-like growth factor 1 receptor (IGF-1R) signaling through heterodimerization with EGFR and HER2 to stimulate glycolysis and trastuzumab resistance." (PMID 34675407, 2022). "First, we determined that overexpression or knockout of GASP1 virtually unchanged mRNA level of IGF1R in breast cancer cells, suggesting that GASP1 positively regulates IGF1R expression at a post-transcriptional level." (PMID 36042202, 2022). "In basal-like breast cancer cells, SPCA1 silencing inhibits the processing of IGF1R, a substrate of proprotein convertases involved in breast cancer progression." (PMID 35805075, 2022). "Here, we demonstrated the IGF-1/IGF-1R signaling axis to induce FASN protein and mRNA expression in breast cancer cells." (PMID 36096767, 2022). "IRS-2-expressing breast carcinoma cells are less invasive after treatment with an IGF-1R/IR small molecule inhibitor, which emphasizes the importance of upstream IGF-1R signaling through IRS-2 for the regulation of invasion." (PMID 36556357, 2022). "These miRNAs appeared to act as tumor suppressors by targeting Insulin-like Growth Factor 1 Receptor (IGF-1R) and Insulin Receptor Substrate 1 (IRS1), often overexpressed in breast cancer." (PMID 34298969, 2021). "First, Herceptin-resistant breast cancer cells over-produced IGF2, triggering autocrine activation of the IGF-1R signaling, which required IRS1 expression." (PMID 33976188, 2021). "We measured protein levels of two receptor tyrosine kinases, Epidermal Growth Factor Receptor (EGFR) and Insulin-like Growth Factor 1 Receptor (IGF-1R), both critical in the processes leading to metastasis in breast cancer." (PMID 34238275, 2021). "In breast cancer, some studies showed crosstalk between DDR1 and the insulin and IGF receptors, IR-A and IGF-1R (Insulin like Growth Factor 1 Receptor)." (PMID 33917302, 2021). "A recent report indicates that the lncRNA NR2F1-AS1 promotes breast cancer angiogenesis via sponging miRNA 338-3p, thereby enhancing IGF1 expression and activating IGF1R signaling." (PMID 33673232, 2021).
breast cancer (continued). "In preclinical breast cancer models, the IGF1/IGF1R/Akt axis sustained mRNA expression of EphB4, thereby promoting cell proliferation and migration responses, which were sentitive to the PI3K inhibitor LY294002." (PMID 34440844, 2021). "In another preclinical study of W0101, animal experiments of MCF-7 (breast cancer, IGF-1R 3+), CAOV3 (ovarian cancer, IGF-1R 2+), NCI-H2122 (lung cancer, IGF-1R 2+), SBC5 (lung cancer, IGF-1R 1+) and Hs746T (gastric cancer, IGF-1R−) were carried out." (PMID 34203870, 2021). "Vitamin D and its analogs have also been shown to suppress IGF-1-induced growth of breast cancer cells by downregulating IGF and IGF-1R and increasing IGF-BP expression." (PMID 35008602, 2021). "IGF1R and HER2 are both members of the growth factor receptor family which is known to play a different role in breast cancer." (PMID 34837929, 2021). "They identified that some genes like MTDH, IGF1R and CDK6 can be affected by miRNAs and can modify cellular processes in breast cancer." (PMID 32635415, 2020). "We interrogated the TCGA provisional dataset for association of gene expression alterations in the IGF signalling components analysed above (IGF-1R, IFG-2R, IGFBP4, IRS-1, IRS-2) with survival in breast cancer." (PMID 32792532, 2020). "In breast cancer, these included VEGF signaling, EGFR signaling, and IGF1R signaling related pathways (all up-regulated in transcriptomics and down-regulated in proteomics)." (PMID 32907876, 2020). "PQ401 has been shown to inhibit autophosphorylation of the insulin-like growth factor I receptor (IGF-1R) and impede breast cancer cell growth in in vivo mouse models." (PMID 32605985, 2020). "The aim of this study was to clarify the signaling pathway between TF and IGF-1R after FVIIa treatment with PC3 and DU145 prostate or MDA-MB-231 breast cancer cells as model systems." (PMID 32458278, 2020). "In breast cancer, DDR1 activates the insulin-like growth factor I receptor (IGF-1R) to support several IGF-1R-mediated biological responses such as cell proliferation." (PMID 32582700, 2020). "In our initial study on IGF1R aAb, we isolated immunoglobulins from adult patients with GO and tested their effects on IGF1 signaling and the proliferation of MCF7 breast cancer cells in vitro." (PMID 31940750, 2020). "In ER/PR-positive and HER2-negative breast cancer patients, the overall and disease-free survival rates did not evidence significant differences between high and low IGF-1/IGF-1R expression groups." (PMID 32325700, 2020). "In conclusion, our study demonstrates that stimulation of IGF‐1R activates the PI3K and MAPK pathways in ER+ breast cancer cell lines, contributing to tamoxifen resistance." (PMID 31490549, 2020). "Mechanically, lncRNA NR2F1‐AS1 increased insulin‐like growth factor‐1 (IGF‐1) expression through sponging miRNA‐338‐3p in breast cancer cells and then activated the receptor of IGF‐1 (IGF‐1R) and extracellular signal‐regulated kinase (ERK) pathway in HUVECs." (PMID 32548873, 2020). "Noteworthy, ERα is also able to synergize with the insulin-like growth factor 1 receptor (IGF1R) in response to 17β-estradiol (E2) and IGF1 stimuli, as showed in the MCF7 breast cancer cell line." (PMID 32645881, 2020). "This positive correlation is particularly evident in ERα+ and ERα- breast cancer patient samples, cancer cell types known to have elevated EGFR and IGF1R expression." (PMID 32340151, 2020). "Several growth factor–related breast cancer genes (EGF, IGF1, IGF1R, IGF2, IGFBP3, IL10, TGFB1, and VEGF), including 26 SNPs, were used as simulation data to evaluate existing algorithms and the proposed HTGA." (PMID 32554381, 2020). "Conversely, estrogen influences the IGF-1 pathway by increasing the expression of both IGF-1R and IRS1 in breast cancer cells." (PMID 30692633, 2019).
breast cancer (continued). "Compelling evidence has demonstrated that several tyrosine kinase receptors, including HER-2, epithelial growth factor receptor (EGFR), and insulin-like growth factor-1 receptor (IGF-1R) participate in acquired endocrine resistance in breast cancer." (PMID 31815253, 2019). "In fact, IGF-1R was the first RTK to be targeted by an inhibitory antibody in preclinical studies, when neutralizing antibody αIR3 was shown to inhibit growth of breast cancer cells in vitro and as xenografts in immunodeficient mice." (PMID 31416218, 2019). "In the present study, we designed the CH-based nanocarrier for co-delivery of DTX and IGF-1R siRNA, and subsequently, MUC1 Apt was conjugated to the NPs for evaluating cell viability and genes expression in metastatic breast cancer cells." (PMID 30041514, 2019). "Ligand-induced migration was inhibited in cells with silenced IGF1R or INSR, indicating that both receptors are involved in breast cancer cell migration." (PMID 31771180, 2019). "As for IGF-1R expression, 85% (68/80) of NEDD4-positive staining breast carcinomas were found to stain positive for IGF-1R whereas only 26.5% (18/68) of BC tissue with negative NEDD4 staining stained positive for IGF-1R." (PMID 31856858, 2019). "Our data reveal that UCA1 upregulates the IGF-1R and PKM2 by competitively sponging miR-122-5p, and thus promotes the invasive potential of breast cancer cells." (PMID 29669595, 2018). "Alternatively, in ER− breast cancers, miR-7 overexpression has been considered as a potential therapeutic strategy to exploit miR-7-mediated suppression of EGFR and IGF1R, which are often overexpressed in triple-negative breast cancer (TNBC)." (PMID 30214383, 2018). "The RTK family includes a number of growth factor-mediated receptors, such as IGF1R, EGFR, and ErbB2/Her2, that are reported to promote several hallmarks of breast cancer." (PMID 30214383, 2018). "Further stratification of ER+/PR+ patients confirmed worse overall survival correlates with low IGF-1R compared to high IGF-1R expression, even within this breast cancer subtype." (PMID 30458886, 2018). "In the un-treated model, proteins (ER-α, IGF-1R, Akt and IRS1) were shown to be over-expressed which leads towards breast cancer metastasis." (PMID 29787591, 2018). "Many strategies targeted the IGF-1R, either with monoclonal antibodies (mAbs) or with receptor tyrosine kinase inhibitors; however, they failed in phase III breast cancer clinical trials." (PMID 30185144, 2018). "IGF1R, EGFR, AXL, VEGFR are other RTK members share common downstream signaling molecules such as PI3K/Akt/mTOR and MAPK with HER2 in breast cancer." (PMID 29455658, 2018). "There is a strong correlation of PDZK1 with multiple signaling pathways including estrogen dependent IGF-1R and chemokine (C-X-C motif) receptor 4 (CXCR4) signaling which can be targeted therapeutically to treat breast cancer." (PMID 29787591, 2018). "In early breast cancer, all CTC‐positive (+) patients harbored IGF1R(+) CTCs, seven (25%) also had IGF1R‐negative (−) CTCs, and none presented exclusively IGF1R(−) CTCs." (PMID 28766847, 2018). "Fulvestrant should be used to inhibit multiple targets (IGF-1R, IRS-1, PDZK1 and ER-α) involved in breast cancer progression." (PMID 29787591, 2018). "Studies showed that increased expression of estrogen by ligand binding interaction (IGFs with IGF-1R) can regulate the downstream signaling mediators such as IRS-1, Akt and PI3k in breast cancer cells." (PMID 29787591, 2018). "Currently, targets such as mTOR, PI3K, IGF-1R, Akt, HSP90, and VEGF exhibited significant clinical interests in HER2-positive breast cancer." (PMID 30134903, 2018). "The coexpression of IGF1R and E‐cadherin was evaluated in cytospins of MCF7, MDA‐MB‐231, and MDA‐MB‐453 breast cancer cells using triple immunofluorescence." (PMID 28766847, 2018).
breast cancer (continued). "We demonstrate that attenuated IGF-1R signaling in the MMTV-Wnt1 mouse mammary tumor model and in human breast cancer cell lines increases tumor epithelial cellular stress, resulting in upregulation of cytokine production." (PMID 30458886, 2018). "So, it is important to note that IGF-1R, IRS-1 and ER-α serve as important inhibitory targets in breast cancer treatment." (PMID 29787591, 2018). "While there are promising preliminary results among breast cancer and NSCLC patients treated with the IGF1R inhibitor Dalotuzumab, according to our results, the subgroup of male patients with NSCLC appears to benefit the most of such a treatment." (PMID 28742836, 2017). "Of note, hyperinsulinemia increases mammary tumor growth in vivo, and blockade of the INSR/IGF1R reduces tumor growth in hyperinsulinemic mice." (PMID 28038446, 2017). "IGF1R, BCL2, and MET, which promotes breast cancer progression and tumor metastasis, composed interaction models with various miRNAs." (PMID 28793339, 2017). "Overexpression of miR-152 significantly inhibited cell proliferation, colony formation and tumor angiogenesis by targeting IGF-1R and IRS1 in breast cancer." (PMID 29162853, 2017). "This study has identified novel relationships between breast cancer patient survival outcome and ER, PR and HER2 status and anti-estrogen therapy, based on IGF1R and SphK1 protein expression." (PMID 29207959, 2017). "Using flow cytometry, we determined the membrane expression levels of all four HER-family members, IGF-1R, c-Met and ALK in our panel of breast cancer cell lines, with expression being represented as mean fluorescence intensity (MFI)." (PMID 28638122, 2017). "Based on the results of previous studies, we chose the miR-122 target genes ADAM10, Bcl-w, VEGFC, PKM2, NOD2, IGF1R and NDRG3 to explore the downstream genes in breast cancer." (PMID 29200969, 2017). "In the present study we used as model systems patient-tumor derived CAFs and SKBR3 breast cancer cells, which allowed us to characterize the IGF1/IGF1R action in ER-negative breast cancer cell setting." (PMID 29212519, 2017). "The selected pIGF1R/InsR antibody was chosen based on a previous publication evaluating the expression of pIGF1R/InsR in breast cancer tissue with IHC, and the specificity by treating DU145 prostate cancer cells with a IGF1R tyrosine kinase inhibitor." (PMID 28030849, 2017). "Inhibitors of STAT3, β‐catenin, and IGF‐1R sensitized H1047R‐derived mouse tumor cells and PIK3CA‐H1047R overexpressing human HS578T breast cancer cells to the cytotoxic effects of PI3K inhibitors." (PMID 28296140, 2017). "Using the T47D breast cancer cell line, IGF-1 induced substantial CELx signals through IGF-1R with an average Delta CI of 0.4." (PMID 28302091, 2017). "Next, ASSIGN was used to estimate the activation of each GFRN member (AKT, BAD, EGFR, HER2, IGF1R, KRAS (G12V), and RAF1) in 1119 breast cancer patient samples from TCGA and 55 samples from the ICBP panel of breast cancer cell lines." (PMID 28446242, 2017). "We recently reported that, in breast cancer cells, IGF-1R functionally crosstalks with DDR1 and this interaction increases IGF-1R stability and enhances protumorigenic actions of IGF-1." (PMID 28591735, 2017). "The IGF2 receptor, IGF1R, is expressed at high levels in cancer stem cell (CSC)-enriched populations in primary breast cancers." (PMID 29099049, 2017). "In this study, we have paid attention to three different GFRs that are highly expressed on breast cancer, namely epidermal growth factor receptors (EGFR1 and ERBB2) and insulin-like growth factor 1 receptor (IGF1R)." (PMID 29119846, 2017). "The cathelicidin peptide LL-37, an IGF-1R agonist, selectively activates ERK leading to enhanced cell migration and invasion of MCF-7 human breast cancer cells." (PMID 28796787, 2017).
breast cancer (continued). "Metformin further inhibits cancer cell proliferation through blockage of the IGF/IGF-1R signaling pathway, as shown in PC-3 prostate cancer cells, MKN1, MKN45, and MKN74 gastric cancer cells, and SKBR3 and BT474 breast cancer cells." (PMID 28193239, 2017). "Estradiol is known to rapidly activate many signaling molecules, including insulin-like growth factor 1 receptor (IGF-IR), epidermal growth factor receptor (EGFR), and mitogen-activated protein kinase (MAPK) in breast cancer cells." (PMID 29104246, 2017). "So far, the direct validated targets of this miRNA include stem cell self-renewal regulator SOX2 in breast cancer, TGFBR1 and FGF9 in hepatocellular carcinoma, SOX9 and ALDH1 in ductal carcinoma in situ and IGF1R in lung cancer." (PMID 26882564, 2016). "BMS-754807 is a reversible ATP competitive dual IGF-1R/IR inhibitor, with an IC50 ranging 100nM to 25μM in breast cancer cell lines and a recommended dose of 100mg daily in patients." (PMID 27472395, 2016). "EGCG interacts with target proteins in the breast cancer cells, such as ERα, Zap-70, PI3K, G3BP1, IGF-1R, vimentin, Bcl-2, Bcl-xL, GRP78, and Fyn via hydrogen bonding, which plays a role in the inhibition of breast cancer." (PMID 27483305, 2016). "Accumulated data has implicated IRA, or the IR total content, as an important factor in breast cancer outcome and implicates IRA as a mechanism of resistance towards therapies specifically targeting IGF-1R, namely monoclonal antibody therapeutics." (PMID 27765027, 2016). "Our findings support evidence demonstrating that growth factor receptors, such as insulin-like growth factor receptor (IGF-1R), EGFR, and ErbB2, play critical roles in the mediation of endocrine resistance in breast cancer." (PMID 27659519, 2016). "Overall, we conclude that suppression of IGF-1R kinase activity or IGF-1R expression levels is sufficient to induce the DNA damage and DNA repair response pathways in breast cancer cells." (PMID 27472395, 2016). "Previous studies have shown that IGF1R activation can induce EMT in prostate cancer, breast cancer, mammary epithelial cells and lung cancer cells." (PMID 27409796, 2016). "Previous report of such feedback loop in breast cancer cells showed that AKT inhibition resulted in up regulation of HER2, HER3, IGF-1R and INSR expression and downstream signaling." (PMID 27819360, 2016). "This novel observation obtained from in vitro study was further evidenced clinically by an inversed correlation between IGF-1R and HRD1 expression in breast cancer tissues." (PMID 26536657, 2015). "Overexpression of HRD1 prevented the formation of breast cancer cell malignant phenotypes and, importantly, suppressed the EMT by degradation of IGF-1R." (PMID 26536657, 2015). "The first assessment of IGF-1R targeted treatment used αIR-3, a mouse monoclonal antibody (mAb), which blocked IGF-1 binding to IGF-1R and inhibited growth of estrogen-independent breast cancers in vitro and in vivo." (PMID 26217584, 2015). "There is some evidence showing differential effects of cytoplasmic IGF1R expression on disease-free survival (DFS) and breast cancer specific survival (BCSS) in ER-positive versus ER-negative breast cancers." (PMID 25749031, 2015). "99mTc-ZIGF1R:4551-GGGC demonstrated specific binding to IGF-1R-expressing DU-145 (prostate cancer) and MCF-7 (breast cancer) cell lines and slow internalization in vitro." (PMID 25425114, 2015). "In the present study we investigated the dynamics of IGF-1R expression during neoadjuvant breast cancer treatment, in order to determine whether the expression of IGF-1R in human breast tumors can be affected by neoadjuvant breast cancer treatment and whether changes are associated with survival." (PMID 25680198, 2015). "We also observed that IGF-1R expression level was negatively correlated with the expression levels of HRD1 (correlation = − 0.507, P < 0.01) in the breast cancer tissues, indicating a potential relationship between IGF-1R and HRD1." (PMID 26536657, 2015).